INS (insulin)
Diseases named in the same sentence as INS in open-access papers (continued):
Sharing a sentence is not in itself a finding about the gene and the disease.
Insulin resistance (continued). "Further, vitamin D deficiency has been linked to higher insulin resistance, lower insulin sensitivity, earlier feelings of hunger, and higher food intake." (PMID 30477276, 2018). "In the following years, several circulating factors associated with systemic insulin resistance were shown to directly disrupt podocyte insulin signaling via several cellular mechanisms, as recently reviewed." (PMID 30524379, 2018). "Early identification of insulin resistant individuals is important for managing the health problems associated with insulin resistance." (PMID 30462805, 2018). "This metabolic disorder involves a progressive loss in the body’s ability to respond to insulin (insulin resistance) resulting in hyperglycemia and the pancreas compensates for this loss causing hyperinsulinemia." (PMID 30258344, 2018). "In contrast, increasing free T concentrations was associated with a higher BMI, as well as higher insulin levels and insulin resistance, but this association disappeared after adjusting for BMI." (PMID 30275830, 2018). "Insulin resistance has been associated to cases of both excess fat and sarcopenia, given that skeletal muscle is one of the major target tissues of insulin action." (PMID 29462978, 2018). "Collectively, iron overload and deficiency are the critical issues in insulin’s action and its association with insulin resistance." (PMID 30043289, 2018). "In obese individuals, hypersecretion of insulin compensates insulin resistance in peripheral tissues caused by elevated levels of circulating fatty acids." (PMID 30134843, 2018). "The SORBS1 gene product, sorbin, is involved in insulin function (i.e., signaling and stimulation) and has been implicated in insulin resistance and the pathogenesis of diabetic nephropathy." (PMID 30524468, 2018). "The major hallmarks of T2D are insulin deficiency and insulin resistance which emphasize insulin therapy in onset of disease." (PMID 29751685, 2018). "Consistently, androgen receptor-deficient mice exacerbates adiposity and insulin resistance induced by a high-fat diet; elevated serum IL-1β levels and decreased pancreatic glucose-stimulated insulin secretion was also observed." (PMID 29867762, 2018). "In this regard, some alterations in the genes associated with insulin signaling have been found in insulin resistance and type 2 diabetes." (PMID 30170598, 2018). "Insulin resistance causes impaired insulin signalling, primarily leading to inhibition of the phosphoinositide 3-kinase (PI3K)/Akt signalling pathway, which in turn results in injury to the nervous systems." (PMID 29598819, 2018). "Adiponectin promotes insulin sensitivity and has anti-inflammatory properties; decreased circulating levels are associated with obesity, insulin resistance, and T2D." (PMID 29483369, 2018). "Another confirmation came from a clinical study demonstrating that only 9 days of oral olanzapine treatment causes significant elevations in postprandial insulin, glucagon-like peptide 1, and glucagon coincident with insulin resistance." (PMID 29740394, 2018). "This metabolic disorder is characterized by relative or absolute deficiency of insulin secretion and/or insulin resistance that cause chronic hyperglycemia and impaired carbohydrates, lipids, and proteins metabolism." (PMID 29558444, 2018). "Pediatric studies have shown that OSA measured by PSG is associated with markers of insulin resistance as measured by fasting insulin and glucose (HOMA-IR), OGTT, and intravenous glucose tolerance testing." (PMID 29910773, 2018). "Pregnancy is associated with maternal β-cell expansion, to account for the increased insulin needs associated with insulin resistance." (PMID 30424584, 2018). "Since glucose uptake by the hippocampus depends on insulin, several lines of investigation have implicated insulin resistance in the development of dementia that manifests late in life." (PMID 30002734, 2018).
Insulin resistance (continued). "Insulin dysregulation refers to basal and/or postprandial hyperinsulinemia, sometimes also associated with tissue insulin resistance." (PMID 29351765, 2018). "Insulin dysregulation is thought to be the key factor linking the metabolic phenotype of obesity and insulin resistance with the increased risk of laminitis (comprising the features of Equine Metabolic Syndrome; EMS)." (PMID 30519508, 2018). "Plasma adiponectin was associated with insulin sensitivity and reduced plasma adiponectin was a marker of insulin resistance and increased risk of type 2 diabetes." (PMID 29794984, 2018). "T2D is characterized by hyperglycemia, caused by insulin resistance in the peripheral metabolic tissues and impaired insulin secretion from β cells." (PMID 29898399, 2018). "It has been shown that a deficiency of Metrnl in adipocytes promotes insulin resistance whereas the upregulation of Metrnl in adipocytes improves insulin sensitivity." (PMID 30212581, 2018). "Decreased mitochondrial CoQ was sufficient to cause insulin resistance via a mechanism requiring mitochondrial oxidants, while restoration of mitochondrial CoQ restored insulin sensitivity." (PMID 29402381, 2018). "On the contrary, insulin resistance characterized by high insulin levels has been associated with increased levels of reactive oxygen species." (PMID 29324783, 2018). "Leucine supplementation caused a more significant reduction in plasma insulin and homeostatic model assessment-insulin resistance (HOMA-IR) index in db/db + Leu mice compared with that of db/db mice." (PMID 29966331, 2018). "Type 2 diabetes, which accounts for 90% of diabetic patients, is characterized by a chronic hyperglycaemia resulting from insulin resistance associated with defects in insulin secretion." (PMID 30429669, 2018). "In conclusion, our results show an important role of T3 treatment on the reduction in the expression of WAT inflammatory cytokines associated to insulin resistance and on the improvement of insulin sensitivity of obese rats." (PMID 29388360, 2018). "Increased hepatic gluconeogenesis occurs in NAFLD, and hepatic insulin resistance is associated with increased insulin secretion required to regulate the normal rate of hepatic glucose production." (PMID 29749571, 2018). "The increased level of pro-inflammatory cytokines, in turn, causes disruptions in insulin signaling, subsequently leading to insulin resistance." (PMID 29414858, 2018). "We suggest that accumulation of ADMA is associated with modulation of insulin signaling and insulin resistance." (PMID 29391561, 2018). "Short-term exposure of TBT (0.025 mg/kg, 3 weeks) has been found to increase blood glucose and plasma insulin levels, and caused the insulin resistance in mice." (PMID 29636531, 2018). "Serum depleted of HSPs, as well as the serum from the insulin-resistant people subjected to a duodenal–jejunal bypass, reverse these features, identifying gut-secreted HSPs as possible causes of insulin resistance." (PMID 30271951, 2018). "Association between mitochondria and insulin resistance have typically been focused on reductions of mitochondrial function in insulin resistant experimental models." (PMID 29538286, 2018). "It is primarily caused by insulin resistance (failure of the body's normal response to insulin) and/or insufficient insulin production by beta cells." (PMID 30054458, 2018). "Since GLUT4 is dependent on insulin for the uptake of glucose and its impairment can cause insulin resistance and the aim of this review is to discuss the insulin signaling pathway, more emphasis has been given on this glucose transporter protein." (PMID 29382104, 2018).
Insulin resistance (continued). "Previous studies have shown that obesity increases peripheral insulin resistance and causes central insulin resistance by decreasing the levels of brain insulin; importantly, peripheral insulin resistance is associated with cognitive impairment." (PMID 29673239, 2018). "Animal and cell culture studies suggest that hyperglycemia can affect bone tissue as well as bone turnover and serum levels of osteocalcin have also been shown to be inversely associated with fasting insulin and insulin resistance in humans." (PMID 29946974, 2018). "Serum retinol binding protein (RBP4) is increased in insulin-resistant states and highly associated with both the magnitude of insulin resistance and individual components of the metabolic syndrome and the risk to develop coronary heart disease in humans." (PMID 29416053, 2018). "One study reported that a lower muscle mass is associated with fewer insulin-responsive target tissues, which would promote insulin resistance and ultimately lead to obesity." (PMID 30258366, 2018). "Weight loss from 3 to 7% led to lower 2 h glucose and insulin levels, as well as improved insulin resistance in men compared to women—above 7% additionally ameliorated triglyceride and HbA1c levels were reported, which was more pronounced in men." (PMID 29780358, 2018). "Lower level of glycogen causes insulin resistance by inhibiting Akt stimulated insulin pathway and lead to steatosis." (PMID 29880906, 2018). "The high chronic exposure to insulin can cause peripheral insulin resistance, which also induces steatosis by increased hepatic lipogenesis." (PMID 29721506, 2018). "Collectively, beneficial effects of omega 3 PUFA on insulin sensitivity can be also due to their effect on reducing ER stress and subsequent inflammatory pathways linked to insulin resistance onset." (PMID 29538286, 2018). "Insulin resistance can also occur if any of the steps in the process of encoding the insulin gene into the glucose metabolism are altered." (PMID 29765322, 2018). "Previous studies have found that smoking and smoking cessation are associated with insulin resistance, which is in accord with lower insulin levels in the smoker group." (PMID 30405010, 2018). "The expression of PTP1B, as well as other phosphatases that negatively regulate insulin signalling, is increased with ageing and has been suggested as an underlying mechanism of age-associated insulin resistance." (PMID 30043179, 2018). "The TCF7L2 gene was reported to be associated with T2D, insulin sensitivity, and insulin resistance." (PMID 29871606, 2018). "Increases in body fat are related to reduced insulin signaling in the HFO, likely contributing to the abolishment of early insulin sensitivity and potentially increasing their risk for insulin resistance later in life." (PMID 29484855, 2018). "Insulin resistance in obese participants was associated with impaired insulin signaling, and reduced levels of glucose-6-phosphate and TCA-cycle intermediates." (PMID 30183740, 2018). "The cross talk between the adipose tissue and insulin target tissues is a key mechanism for obesity-associated insulin resistance." (PMID 29930536, 2018). "In contrast, increasing free T or decreasing SHBG concentrations were associated with a higher BMI, as well as higher insulin levels and insulin resistance, but this association disappeared after adjusting for BMI." (PMID 30275830, 2018). "These mice showed that loss of insulin signaling in hepatocytes leads to severe primary hepatic insulin resistance, glucose intolerance and chronic hyperinsulinemia, in part caused by impaired insulin clearance." (PMID 30314283, 2018). "PPARGC1A overexpression in liver has been associated with hepatic insulin resistance, manifested by higher glucose production and impaired suppression of gluconeogenesis in response to insulin in transgenic mice." (PMID 30540820, 2018).
Insulin resistance (continued). "Adipose tissue is one of the major targets of insulin, and disruptions in glucose uptake in adipose tissue is associated with insulin resistance." (PMID 30347867, 2018). "Obesity-induced inflammation has also been linked to the development of insulin resistance, even when controlling for BMI, indicating the additional physical stress of being insulin resistant on increasing chronic inflammation beyond fat mass." (PMID 30538987, 2018). "Dietary anthocyanins have also been associated with improvements in insulin sensitivity, making them a potential dietary ammunition against insulin resistance." (PMID 29601521, 2018). "Changes in the ratio of plasma and urinary myoIns/DCIns levels are so tightly linked to insulin abnormalities to be considered an early marker of hyperglycemia and insulin resistance." (PMID 30595691, 2018). "More than 95% of diabetic patients have type 2 DM (T2DM), causing hyperglycemia via an ineffectiveness of insulin action or an inability to mount a normal response to insulin in peripheral cells, resulting in the symptoms of insulin resistance." (PMID 29342975, 2018). "The reduced intake of sugary drinks improved insulin sensitivity, which can be explained by the association between sugar intake and insulin resistance." (PMID 29324776, 2018). "Type 2 diabetes (T2D) is also caused by increased insulin resistance and decreased insulin secretion to compensate for the former." (PMID 30089489, 2018). "A reason for this variation in cholesterol metabolism is related to altered insulin resistance suggesting that better insulin sensitivity is linked to a higher cholesterol absorption." (PMID 29795368, 2018). "In other studies, women have been identified as being distinctly different than men with regard to insulin action, susceptibility to develop insulin resistance, and response to stimuli that are known to enhance or impair sensitivity to the effects of insulin." (PMID 30138332, 2018). "Contrary to humans, fat deposition appears to be associated with insulin sensitivity and fat loss with insulin resistance in bears." (PMID 30151194, 2018). "In mice, hepatic HPS overexpression induced insulin resistance, while its knockdown was associated with improved insulin sensitivity in high-fat fed mice." (PMID 30200408, 2018). "Outside of environmental factors that contribute to insulin resistance, genetic variations in the insulin signaling pathway have also been linked to NAFLD progression and fibrosis." (PMID 30355853, 2018). "On the contrary, inhibition of autophagy by CQ further exacerbated T-impaired mitochondrial function and insulin-stimulated glucose uptake, causing insulin resistance." (PMID 29552281, 2018). "Food rich in PUFA increases insulin sensitivity, glucose utilization and decreases insulin resistance and the risk of type 2 diabetes." (PMID 29867133, 2018). "In conclusion, AGM improved glucose metabolism by potentiating insulin secretion and reducing insulin resistance in insulin deficient type 2 diabetic rats." (PMID 30041479, 2018). "Loss of endothelial insulin-induced vasorelaxation is considered an important linking insulin resistance and CVDs in obesity and metabolic diseases." (PMID 30416448, 2018). "Whereas some genetic or pharmacologic interventions that specifically compromise mitochondrial function have been shown to cause insulin resistance, other genetic interventions that impair mitochondrial function actually improve whole-body insulin action." (PMID 29599292, 2018). "The combination of reduced glucose uptake and impaired insulin signaling in these HCV protein expressing mice was interpreted as the cause of insulin resistance." (PMID 28991180, 2017). "One such explanation is that Asians have a genetic predisposition for insulin resistance due to mutations in various genes that code for proteins along the insulin pathway." (PMID 28640854, 2017).
Insulin resistance (continued). "Recent studies have shown that FFAs not only are the major causes of insulin resistance, but they are also responsible for inducing inflammatory events in the tissues targeted by insulin, such as ECs, liver and skeletal muscle." (PMID 28750629, 2017). "Type 2 diabetes(T2D) is a metabolic disorder characterized by high blood glucose levels and defective carbohydrate utilization due to a relative or absolute deficiency of insulin or insulin resistance with impairment of β-cell function." (PMID 28425473, 2017). "Impaired insulin signalling in skeletal muscle and adipose tissue has a pathogenic role in conditions of insulin resistance." (PMID 29178904, 2017). "Numerous studies have implicated CD11c+ ATMs in the development of insulin resistance, and RS-mediated improvements in insulin sensitivity in rats have been associated with reduced CD11c expression in adipose tissue." (PMID 28166818, 2017). "In another clinical study, IGF-1 combined with IGFBP-3 has been shown to improve insulin sensitivity and to reduce complications associated with insulin resistance in HIV/AIDS patients on antiretroviral therapy." (PMID 29422987, 2017). "Numerous studies suggest that peripheral insulin resistance and/or impaired insulin secretion are causative factors for diminished carbohydrate metabolism." (PMID 28459862, 2017). "This inflammation, if chronic, extends to the pancreas where insulin secretion defects occur, to the skeletal muscle in association with insulin resistance and to the liver, where both insulin resistance and hyperglycemia develop." (PMID 29138671, 2017). "Molecular analysis has shown that the whole body insulin resistance is associated with changes in insulin signaling protein expression, especially in adipose tissue." (PMID 28291256, 2017). "Insulin resistance and the subsequent production of excessive amounts of insulin are directly associated with the increased ovarian production of androgens and the features of PCOS." (PMID 32153805, 2017). "The effect of α-glucans has been associated with increased insulin sensitivity and improved insulin resistance in peripheral target tissues, therefore they have been demonstrated to induce an anti-diabetic effect." (PMID 28718825, 2017). "Under metabolic syndrome, insulin signaling in adipose tissue is perturbed, associated with insulin resistance and chronic inflammation." (PMID 28972997, 2017). "Obesity is also known associated with high serum insulin and insulin resistance, which are risk factors of developed PCa." (PMID 29029491, 2017). "Insulin resistance causes type 2 diabetes; therefore, increasing insulin sensitivity is a therapeutic approach against type 2 diabetes." (PMID 29259227, 2017). "Insulin resistance (fasting insulin and HOMA-IR) has previously been associated with declines in cognition in middle-aged and older adults, including slower CPS." (PMID 28344553, 2017). "Excess ectopic fat storage has been linked to insulin resistance, and pancreatic fat content has been negatively associated with insulin secretion." (PMID 28742102, 2017). "We observed a decrease in the long chain Cer (18:1/20:0) assumed to be associated with insulin resistance, but also a decrease in the very long-chain sphingomyelin SM (d18:1/24:1) that is presumably associated with increased insulin sensitivity." (PMID 28398243, 2017). "These indicated that insulin resistance and downregulated insulin signaling activities are associated with AD pathologies in patients." (PMID 28282917, 2017). "The relationship between mitochondrial dysfunction and insulin resistance in many chronic disease states provides a strong rationale for impaired insulin signaling in the etiology of cancer-associated anabolic resistance in muscle." (PMID 29375734, 2017). "Insulin resistance (IR) or low insulin sensitivity is associated with obesity and metabolic syndrome." (PMID 29101482, 2017).